IL6 (interleukin 6)
Diseases named in the same sentence as IL6 in open-access papers (continued):
Sharing a sentence is not in itself a finding about the gene and the disease.
Stroke (continued). "While pro-inflammatory macrophages worsen tissue damage during stroke via the release of pro-inflammatory mediators (tumor necrosis factor-α, IL-12, IL-6, IL-1β, nitric oxide, etc.), anti-inflammatory cells are primarily phagocytic and release anti-inflammatory mediators." (PMID 30322390, 2018). "IL-6 expression was increased in macrophages and endothelial cells from Stroke animals." (PMID 30290827, 2018). "Among the cytokines known to be associated with inflammation in stroke, interleukin-1 (IL-1) and TNF-α were reported to aggravate cerebral injury; in contrast, interleukin-6 (IL-6), interleukin-10 (IL-10), and transforming growth factor-β (TGF-β) were shown to be neuroprotective." (PMID 29090015, 2017). "They suggested IL-6 inducing hyperfibrinogenemia might act a pivotal part as a trigger of procoagulatory in the development of stroke in patients with POEMS syndrome." (PMID 29179528, 2017). "The rates of hypertension (p = 0.03) and T2D (p < 0.001), as well as the levels of HbA1c (p = 0.008), LDL cholesterol (p = 0.003), and inflammatory markers such as hsCRP (p = 0.01) and IL-6 (p < 0.001), were significantly higher in patients with stroke than in the control subjects." (PMID 28166278, 2017). "In patients, the magnitude of this IL-6 response correlates positively with stroke severity." (PMID 28798136, 2017). "Moreover, serum levels of TNF-α and IL-6 decreased, whereas IL-10 increased in stroke patients between day 1 and day 3 (all p < 0.05)." (PMID 27682880, 2017). "Previous reports have shown that TNF-α, IFN-γ, IL-6, IL-17, IL-23, and some monocytes are detrimental in the pathologic process of stroke, whereas Treg cells, IL-4, IL-10, and TGF-β are major cerebroprotective modulators of post-ischemic inflammatory brain damage." (PMID 27682880, 2017). "Cytometric bead assay revealed a significant increase of interleukin-6 (IL-6) or chemokine ligand 2 (CCL2) protein levels in the ipsilateral cortex of mice suffering from stroke compared with corresponding contralateral cortex or to corresponding sham-operated mice." (PMID 28079884, 2017). "The delayed elevation of IL-6 in the serum of patients with cerebral ischemia might be secondary to ischemia; this is in line with the literature from stroke research." (PMID 29194369, 2017). "Moreover, higher plasma levels of IL-6 are taken as a predictive marker of poor outcome in stroke patients." (PMID 29054968, 2017). "However, while IL-6 dropped to sham levels by 24 hours post-stroke in young mice, it remained increased in aged mice at 24 hours (p<0.05) with a similar trend at 72 hours compared to sham (n=5-8/group)." (PMID 27115295, 2016). "Although experimental studies have proven stroke-induced immunodepression by showing decreased peripheral IL-6 production, numerous clinical studies have found that IL-6 expression actually increases after stroke in response to strong inflammatory reactions induced by ischaemic brain injury." (PMID 27409177, 2016). "Despite these conclusive findings in both acute and chronic phases that clearly indicate an important role of IL-6 in stroke patients, these associations are not fully understood." (PMID 27146847, 2016). "In previous studies, the different timing of blood sampling has blurred a distinction whether interleukin-6 could serve as a marker of simultaneously evolving post-stroke infections or rather as their predictor." (PMID 27152948, 2016). "In C57BL/6 mice at 7 weeks post-stroke there were increased levels of G-CSF, GM-CSF, IFNγ, IL-1α, IL-5, IL-6, IL-12 (p40), IL-12 (p70), IP-10, KC, MCP-1, MIP-1α, MIP-1β, MIP-2A, RANTES, and TNFα within the infarct compared to the equivalent area of cortex from sham mice." (PMID 27600707, 2016). "In humans, IL-6 is involved in the acute phase response that follows cerebral ischemia, and there is a correlation between high plasma levels of IL-6 and occurrence of early neurological deterioration following stroke and progression of lacunar infarction." (PMID 25333814, 2015).
Stroke (continued). "We hypothesized that levels of lipopolysaccharide binding protein (LBP), interleukin-10 (IL-10), IL-6 and C-reactive protein (CRP) are early predictors for the development of stroke-associated infection." (PMID 25613713, 2015). "Other SNPs in genes involved in inflammation (APOE and IL6), oxidative stress (NOS3 and SOD2), and As metabolism (AS3MT, CBS, GSTO1, and MTHFR) showed nominally significant interactions with well-water As for associations with CVD, CHD, or stroke." (PMID 25575156, 2015). "By contrast, in stroke animal models, IL-6 appears to play a neuroprotective role, suggesting that its rapid and persistent elevation in the ischemic brain may represent a compensatory mechanism to counteract the damaging effects of the insult." (PMID 25972779, 2015). "IL-6 is pleiotropic and is expressed at a high rate following stroke; however, it remains to be elucidated whether IL-6 is pro-inflammatory, anti-inflammatory, or both." (PMID 25815894, 2015). "Similarly, stroke patients with severe OSA exhibit increased levels of serum IL-6 when they also show hypertension." (PMID 25944984, 2015). "Therefore, we measured serum levels of IL-6 and TNFα in CaMKK β and CaMK IV KO mice 72 hours after stroke." (PMID 25331941, 2014). "Finally, we demonstrated that the levels of the pro-inflammatory serum cytokines TNFα and IL-6 increased after stroke in both CaMKK β and CaMK IV KO mice, indicating that inhibiting this pathway exacerbates the inflammatory response." (PMID 25331941, 2014). "A subset of these cytokines including IL-6 was also suppressed by IGF-1 at 24h post-stroke." (PMID 24618563, 2014). "Finally, inhibiting this pathway exacerbated the inflammatory response to stroke as CaMKK β or CaMK IV KO mice had increased levels of the pro-inflammatory serum cytokines tumor necrosis factor alpha (TNFα) and interleukin 6 (IL-6) after stroke." (PMID 25331941, 2014). "Furthermore, white blood cell counts and levels of C-reactive protein, serum/plasma interleukin-6 (IL-6) and tumour necrosis factor-α (TNF-α) are increased in stroke patients; several of these factors have been associated with stroke outcome and recurrence." (PMID 24889329, 2014). "Despite the impaired pro-inflammatory MCP-1 and IL-6 in the ischemic brain and LPS-stimulated macrophages, increased stroke-induced brain injury in diabetic conditions suggests a benefit of rapid inflammatory response following stroke." (PMID 24886035, 2014). "The inflammatory status, primed by acute cerebrovascular accident and possibly persisting over time by poststroke infarction complications, reduces protein synthesis and increases breakdown, also via IL-6 stimulated hypothalamus-pituitary cortico surrenal axis." (PMID 25431770, 2014). "Although the source of circulating IL-6 during the acute phase of stroke is still unknown, the early increase in IL-6 and its correlation with poor outcome support the role of acute inflammation in the pathophysiology of stroke." (PMID 23497639, 2013). "Further studies are required to clarify the role of IL-6 in stroke." (PMID 23431245, 2013). "Furthermore, during the late subacute/chronic phase (≥17 days after stroke), IL-6 level was positively correlated with the percentage of intermediate Mo (r=0.661, p=0.001; Spearman’s rank correlation coefficient, data not shown)." (PMID 23936327, 2013). "Based on our results, it is tempting to speculate that post-ischemia reperfusion and re-oxygenation might increase microglial expression of IL-6 in stroke patients with hypoglycemia." (PMID 23520526, 2013). "Both IL-6 and IL-17A in serum reached a peak level during the acute phase (3-7 days) after stroke." (PMID 23936327, 2013). "Previous studies demonstrated that IL-6 is one of the predictors of poor outcome in stroke." (PMID 23497639, 2013).
Stroke (continued). "Indeed, patients sampled after 3 h displayed concentration of GST-π, NDKA, DJ-1 close to normal levels whereas the IL-6 concentration displayed a slight but significant second increase at 24 h after stroke onset." (PMID 23028472, 2012). "IL-1β may be a more important target for prevention or treatment of stroke when compared with IL-6 and TNF-α." (PMID 23326018, 2012). "Thus in case of stroke, the relationship between IL-6 and ADMA is contrary to the observations in cell cultures." (PMID 23158556, 2012). "CSF IL-6 content seems to be the most reliable prognostic indicator in the acute phase of ischemic stroke, with regard to the probability of infarct size, the clinical course of disease and the functional outcome of stroke at one month." (PMID 21450100, 2011). "In this study, we analyzed whether the altered expression of IL-6, IL-1β and G-CSF in MCP-1-deficient mice has an influence on the post-stroke migration of neutrophil granulocytes and T-cells." (PMID 22031820, 2011). "In stroke patients, increased cerebrospinal fluid and/or circulating IL-1β, IL-6, IL-10, and CXCL-1 (CINC-1/IL-8), monocyte chemoattractant protein-1, and TNF-α concentrations have been reported, and IL-6 in particular identified as a predictor of stroke outcome." (PMID 21714902, 2011). "The role of endogenous interleukin-6 in post-stroke inflammation and development of brain tissue damage still remains unclear." (PMID 22031820, 2011). "In addition, we and others have described several immunological markers including CD4+ T-cell counts, serum IL-6 levels, and TNF-α release by macrophages that are associated with the occurrence of infection in stroke patients." (PMID 20090932, 2010). "We previously showed that the burden of Chlamydia pneumoniae in carotid plaques was significantly associated with plaque interleukin (IL)-6, and serum IL-6 and C-reactive protein (CRP), suggesting that infected plaques contribute to systemic inflammatory markers in patients with stroke risk." (PMID 20543948, 2010). "Raised levels have also been associated with various conditions considered to be risk factors for dementia and/or AD: subclinical and clinical cardiovascular disease and the risk thereof, type 2 diabetes and its risk, psychological stress and the damage following stroke (IL-6 also increased in CSF)." (PMID 19698145, 2009). "The association was independent of stroke severity, age, and risk factors for recurrent stroke, though only IL-6 was independent of other markers." (PMID 19901973, 2009). "For example, those with higher IL-6 were not at increased stroke risk when assigned to estrogen plus progestin (odds ratio 1.28) but were when assigned to placebo (odds ratio 3.47; p for difference = 0.02)." (PMID 17571161, 2007). "Cytokines such as interleukin(IL)-1, tumour necrosis factor-α (TNF-α) and IL-6 appear to be crucial mediators of such responses, yet much remains unknown about their complex interactions in the setting of clinical stroke." (PMID 17328808, 2007). "In a recent prospective study of ischaemic stroke patients, recruited early (within 12 h) after onset of symptoms, we reported early induction of established markers of inflammation, including interleukin-6 (IL-6), and strong relationships between these and both stroke severity and outcome." (PMID 17328808, 2007). "Furthermore, this meta-analysis revealed that IL-6 was associated with an increased risk of MACE in stroke subtypes related to large artery atherosclerosis, small vessel occlusion, and stroke of undetermined cause, with RR values of 2.30, 1.71, and 1.78, respectively." (PMID 40217803, 2025). "However, IL-6 may have dual effects in brain tissue - in the early stage of stroke it shows pro-inflammatory activity, while in later stages, it has a potentially neurotrophic effect." (PMID 40520895, 2025).
Stroke (continued). "Additionally, IL-6 was significantly associated with stroke outcomes, consistent with findings from Mendelian randomization studies identifying IL-6 as a causal mediator of ischemic stroke in non-AF populations." (PMID 40744929, 2025). "In addition, the use of an anti-inflammatory treatment targeting IL-6 may seem like an important tool in the treatment of strokes." (PMID 40305179, 2025). "Increased IL-6 levels in the cerebrospinal fluid at 6 h post-stroke have been shown to correlate with the degree of neurological deficit, assessed on days 1 and 7 post-stroke using the NIHSS, as well as with functional deficits measured by the Barthel index (BI)." (PMID 40305179, 2025). "On the other hand, neutrophil activation is also linked to increased IL‐6 and TNF‐α levels, which enhance endothelial dysfunction and promote a prothrombotic state, thereby explaining the association between high NLR and increased risk of stroke and systemic embolism." (PMID 39985306, 2025). "Therefore, consideration could be given to introducing cell-based therapies into stroke treatment that can respond to local environments and increase or decrease IL-6 signaling." (PMID 40305179, 2025). "Therefore, IL-6 may be responsible for cognitive disturbances after a stroke, as it is one of the main regulators of the acute-phase response to inflammation and tissue damage, and its concentration is elevated in patients with PSCI." (PMID 40305179, 2025). "In addition, it is worth exploring whether the combination of PCSK9 inhibitors with immunomodulatory drugs such as IL-6 antagonists synergistically ameliorates immune disorders after stroke." (PMID 41368357, 2025). "Notably, pro-inflammatory responses are not exclusive to post-stroke pathology but are also a hallmark of depression, with elevated levels of cytokines such as IL-6 and TNF-α observed in depressive patients." (PMID 40144659, 2025). "Additionally, studies had to report at least one of the following outcomes: incidence of MACE (e.g., myocardial infarction, stroke, or cardiovascular death), levels of inflammatory biomarkers (hs-CRP or IL-6), or adverse events associated with the intervention." (PMID 40688868, 2025). "Additionally, previous studies have indicated that inflammatory mediators such as C-reactive protein (CRP) and interleukin-6 (IL-6) undergo changes during the acute phase of stroke, serving as potential biomarkers for stroke prognosis or imminent complications." (PMID 38509177, 2024). "Under pathological conditions such as stroke, astrocytes become reactive, markedly increasing the expression of glial fibrillary acidic protein (GFAP), the hallmark signature of reactive gliosis, in response to intercellular signaling molecules including IL-6, TNFα, TGF-β, INFγ, and IL-10." (PMID 38854014, 2024). "However, the relevance of IL-6 is not restricted to post-stroke pathophysiology: a recent meta-analysis showed a linear positive relationship between IL-6 serum levels and the risk of suffering from ischemic stroke." (PMID 39372701, 2024). "Frail patients have been shown to have elevated inflammatory markers, including C-reactive protein, IL-6, and TNF-α, and elevated levels of Factor VIII and D-dimer, which raise concern for an underlying coagulopathic state which may predispose them to stroke and myocardial infarction." (PMID 38276658, 2024). "Indeed, IL-6 plasma levels predict stroke size, functional outcome as well as recurrence." (PMID 36745280, 2023). "Indeed, IL-6 is strongly associated with the future risk of major cardiovascular events, including atherothrombosis, and inhibition of the IL-6 signalling pathway may be beneficial for coronary artery disease, stroke, and arterial fibrillation." (PMID 37741880, 2023).
Stroke (continued). "Actually, while some studies found that this molecule might not have a direct influence on ischemic stroke, on the other hand, recent evidence shows that IL-6 can exert neuroprotective effects in course of stroke, especially at later time points by facilitating neurogenesis and functional recovery." (PMID 36745280, 2023). "Furthermore, previous studies have demonstrated that HGS weakness was associated with increased level of inflammatory factors, such as C-reactive protein and interleukin-6, which in turn could contribute to a heightened vulnerability to stroke incidence." (PMID 37908684, 2023). "In addition to blocking IL‐6 signaling, amplification of IL‐6 may offer equally therapeutic benefits to improving stroke prognoses, depending on the time course and each patient's unique inflammatory responses." (PMID 36478506, 2023). "After adjustment for potential confounders, the highest quartiles of IL-6 (adjusted HR 1.36; 95% CI 1.13–1.64; P = 0.001), hsCRP (adjusted HR 1.41; 95% CI 1.17–1.69; P = 0.0003) and YKL-40 (adjusted HR 1.28; 95% CI 1.06–1.56; P = 0.01) were associated with increased risk of recurrent stroke." (PMID 35761288, 2022). "Furthermore Interleukin(IL)-6 levels are positively correlated with stroke severity." (PMID 36555901, 2022). "Cell-based therapies may be fundamental to inducing ideal IL-6 signaling in stroke recovery." (PMID 36555094, 2022). "In addition, administration of muscimol to microglia stimulated with lipopolysaccharide (LPS)/interferon-γ, the latter typically shows elevated levels following stroke significantly reduced the level of pro-inflammatory cytokines interleukin 6 (IL-6) and tumor necrosis factor alpha (TNFα)." (PMID 35401118, 2022). "We therefore aimed to investigate the association of five markers of acute inflammatory—CRP, IL‐6, WBC, neutrophil, and lymphocyte with four poor outcomes defined by overall mortality, NIHSS, mRS, and BI after ischemic stroke in a large retrospective cohort study of stroke patients." (PMID 33314753, 2021). "We hypothesize that—comparable to its effects after stroke—paracrine IL-6 might induce beneficial remodeling processes in the acute phase after modest cerebral hypoperfusion induced by carotid artery disease while it might have detrimental effects in the long-term." (PMID 35155612, 2021). "Elevated levels of IL-6 and TNF-α in the spinal cord after stroke upregulate the concentrations of GAP-43 (growth-associated protein 43), NT-3 (neurotrophin-3), and BDNF, all of which are known to be involved in spinal axonal plasticity and lead to better spontaneous post-stroke recovery." (PMID 33042113, 2020). "In addition, previous studies indicated that Prx1 could significantly induce the expression of TNF-α, IL-1β, and IL-6 via the Toll-like-receptor-4a-mediated NF-κB signaling pathway in stroke." (PMID 32317937, 2020). "Elevated IL-6 levels in the CSF of acute stroke patients have been shown to correlate with infarct volume and functional outcome, while plasma IL-6 levels obtained within the first week of stroke debut correlated with brain infarct volume, stroke severity and long-term outcome." (PMID 32595585, 2020). "To investigate whether the CD200/CD200R signaling pathway is involved in regulating microglia activation and inflammatory factor release after stroke in rats, we assessed microglia activation using immunofluorescence and inflammatory factor (such as Il-1β, Il-6, Tnf-α, Il-4, and Cd206) release." (PMID 32473633, 2020). "However, use of other biomarkers (troponin, NT-proBNP, and cystatin-C) attenuated the importance of IL-6 such that it was no longer predictive of stroke risk in AF." (PMID 32154260, 2020). "Hyperforin could promote post-stroke SVZ neurogenesis, angiogenesis and functional recovery through inhibiting Th1 cell differentiation while promoting Th2/Tregs cells differentiation in the ischemic hemisphere, which is mediated by astrocytic IL-6 during stroke recovery." (PMID 31133816, 2019).